EGFR (epidermal growth factor receptor)
Diseases named in the same sentence as EGFR in open-access papers (continued):
Sharing a sentence is not in itself a finding about the gene and the disease.
head and neck cancer (continued). "Epidermal growth factor receptor (EGFR) inhibition is a good target for the treatment of diverse metastatic epithelial cancers, including lung, colon, pancreatic, and head and neck cancers." (PMID 33113881, 2020). "In head and neck cancer it has been shown that 83% of tumors show overexpression of epidermal growth factor receptor (EGFR) which is commonly utilized in targeted therapies." (PMID 31940973, 2020). "There was a significant difference of p value 0.025 among the ages >40 and ≤ 40 when the high and low level of EGFR was compared in the head and neck malignant tumor." (PMID 33273921, 2020). "Some studies support the use of cetuximab, which mediated antibody-dependent cytotoxicity (ADCC) against epidermal growth factor receptor- (EGFR-) overexpressing tumor cells, and PD-1 blockade can reverse NK cell dysfunction in head and neck cancer." (PMID 32411806, 2020). "Consistently Sym004 efficacy and potentiation of cisplatin responses correlated with EGFR surface expression in head and neck cancer cells." (PMID 31959764, 2020). "On the other hand, in head and neck carcinoma cells it was established that activation of CD44 in complex with the EGFR (epidermal growth factor receptor) signals the release of Ca2+ from the endoplasmic reticulum, leading to CaMK-II activation." (PMID 31991573, 2020). "Targeted therapy specifically directed towards EGFR has been an area of keen interest in head and neck cancer research, as EGFR is potentially an integration point for convergent signaling." (PMID 30700700, 2019). "This review article will discuss recent multilateral efforts to discover and validate actionable strategies that involve signaling pathways in heterogenous head and neck cancer and to overcome anti-EGFR resistance in the era of precision medicine." (PMID 30700700, 2019). "Cetuximab is a targeted drug for EGFR and is the only molecularly targeted therapy for head and neck cancer, but cetuximab is only effective in 10–13% of patients with head and neck cancer." (PMID 31139565, 2019). "Radiotherapy can induce epidermal growth factor receptor (EGFR) expression in head and neck cancers, resulting in acquired resistance." (PMID 30449623, 2019). "In order to study the role of IKK/NF-κB to regulate EGFR inhibitor resistance in head and neck cancers, we cultured Cal27 cells in media that initially contained 0.5 μM of Gefitinb, which was increased to 5 μM over a 6-month span." (PMID 30585254, 2019). "HPSE also enhances the phosphorylation of Src and epidermal growth factor receptor (EGFR), activating STAT3, which is associated with head and neck cancer progression." (PMID 31013618, 2019). "Transforming growth factor-α (TGF-α)-mediated epidermal growth factor receptor (EGFR) signaling plays a vital role for the activation of STAT3 in some head and neck cancer cell lines." (PMID 30847297, 2019). "E1A was shown to supress epidermal growth factor receptor (EGFR) expression leading to decreased activation of growth factor pathways in head and neck cancer cells." (PMID 31817939, 2019). "The cell cycle regulatory gene CCND1 located in 11q13.3 is a downstream effector of EGFR and is commonly deregulated in various cancers including head and neck cancer." (PMID 31159251, 2019). "Activating mutations of the epidermal growth factor receptor (EGFR) gene are well-characterized in non-small cell lung cancer (NSCLC), breast, colorectal, head and neck cancer, and other malignancies." (PMID 30743998, 2019). "Despite the latest advancements in cancer diagnostics and therapeutics against EGFR, the survival rates of patients with advanced head and neck cancer remain disappointing due to anti-EGFR resistance." (PMID 30700700, 2019). "Another strategy is to express a truncated form of human epidermal growth factor receptor (EGFR), which enables the cells to be deleted by cetuximab, a chimeric antibody used to treat EGFR-expressing colorectal and head and neck cancer." (PMID 31447852, 2019).
head and neck cancer (continued). "A recent clinical trial of epidermal growth factor receptor (EGFR)‐targeted PIT in patients with inoperable head and neck cancer has shown promise in a Phase 1/2 clinical trial (NCT02422979)." (PMID 31674732, 2019). "In the present study, we evaluated the interest of inhibiting the EGFR/mTOR/HIF-1 axis to radiosensitize head and neck cancer cells based on combining the anti-EGFR monoclonal antibody cetuximab and the mTOR inhibitor rapamycin." (PMID 31640284, 2019). "The authors additionally reported that the radioconjugate can monitor the effects of EGFR inhibition combined with irradiation in head and neck carcinoma models." (PMID 30213849, 2019). "Recent findings in head and neck cancer show that FGFR3-TACC3 fusion is capable of substituting for EGFR signaling in HNSCC models, and confers resistance to EGFR targeting in HNSCC and possibly in other cancers." (PMID 29933636, 2018). "In this trial, patients were injected with cextuximab-IR700 conjugate, (referred to as RM1929 in the study), that binds EGFR on the cell membrane of head and neck cancers." (PMID 29721181, 2018). "In head and neck cancer, an EGFR inhibitor is one of the major therapeutic modalities for HNSCC and is routinely used in clinical practice." (PMID 30513726, 2018). "Based on expression data, Epidermal Growth Factor Receptor (EGFR) emerged as therapeutic target in Head and Neck Cancer but clinical efficacy of EGFR inhibitors was very limited." (PMID 29989001, 2018). "Recently, cetuximab-IRDye800, targeting the epidermal growth factor receptor (EGFR) in head and neck cancer patients, has been shown to be highly specific for subclinical or non-palpable disease." (PMID 29623552, 2018). "In this study, we analyzed the immune regulatory properties of EGFR signaling in head and neck cancer cells and showed that it suppresses type 1 cytokine-induced expression of CCL2, CCL5, CXCL9, CXCL10 and IL-6 while promoting the expression of IL-1β." (PMID 30192802, 2018). "Honokiol has also been reported to target EGFR signaling via STAT3 in the treatment of head/neck cancer, thus enhancing the effects of EGFR-targeting therapies." (PMID 30587839, 2018). "Previous studies demonstrated that CD137 stimulation of NK cells enhances mAb-mediated ADCC functions and works in synergy with anti-CD20, anti-HER2, and anti-EGFR mAbs in xenotransplant murine models of lymphoma, breast, colon, and head and neck cancer." (PMID 30321186, 2018). "Anti-EGFR antibodies, including cetuximab and panitumumab, are promising molecularly targeted drugs for head and neck carcinomas including AdCC." (PMID 29682203, 2018). "We chose to validate the effect of these HKGs on EGFR expression in the head and neck cancer cell line SCC6." (PMID 28262749, 2017). "We fail to detect EGFR endocytosis or nuclear transport following X-ray treatment of HeLa or head and neck cancer cells, despite extensive DNA damage induction." (PMID 28646091, 2017). "ELISpot was carried out to quantify EGFR-specific T cells in nimotuzumab-treated head and neck cancer (HNSCC) patients." (PMID 28674498, 2017). "In previous trials that focused primarily on brain malignancies or head and neck cancer, nimotuzumab has demonstrated greater efficacy similar to other anti-EGFR mAbs." (PMID 27823977, 2017). "Recent findings have indicated that epidermal growth factor receptor (EGFR) and its signaling transduction pathway play an important role in head and neck cancer in Taiwan, including areca quid (AQ) associated OSCC3." (PMID 28694429, 2017). "On the other hand, the synergy between cetuximab and celecoxib on tumor growth inhibition, induction of apoptosis, inhibition of EGFR activity and drug resistance have been described in head and neck cancer and other tumor types." (PMID 28423516, 2017). "Dysregulation of EGFR in several tumors including lung cancer, head and neck cancer, esophageal cancer, and others, correlated with metastasis and poor survival outcome." (PMID 27823977, 2017).
head and neck cancer (continued). "OSCC is the major head and neck cancer in Taiwan and mechanisms regulating levels of EGFR protein expression in OSCC are not fully understood." (PMID 28694429, 2017). "EGFR-TKIs also prolong survival in a subset of patients with colon, pancreatic, or head and neck cancer WT for EGFR." (PMID 29069773, 2017). "Non-small cell lung cancers (NSCLC) and head-and-neck cancers (HNC) also showed EGFR overexpression." (PMID 28445134, 2017). "Targeted treatments for head and neck cancer focus on inhibition of the epidermal growth factor receptor (EGFR), particularly with the anti-EGFR antibody cetuximab." (PMID 28099487, 2017). "Because overexpression of EGFR is observed in the majority of human HNSCC, HSC3 cells is considered to be a suitable model to recapitulate human EGFR-dependent head-and-neck carcinoma." (PMID 29268862, 2017). "EGFR overexpression has been observed in many different cancers, including gliomas, sarcomas, and head and neck cancers." (PMID 27016412, 2016). "Targeted therapy in head and neck cancer developed with the recognition that epidermal growth factor receptor (EGFR) is overexpressed in the majority of head and neck cancers, up to 90 per cent in some studies, and is associated with a poorer prognosis." (PMID 27841142, 2016). "Recent reports indicate that PPP has the ability to inhibit the phosphorylation status of EGFR in combination with erlotinib or alone in head and neck cancer." (PMID 27716204, 2016). "The upregulation of IL-8 in response to EGFR inhibition has been previously observed in other systems; for example, head and neck cancer cells resistant to erlotinib showed enhanced IL-8 secretion in the context of EMT." (PMID 27248176, 2016). "Recent studies have shown that Tid1-L functions as a tumor suppressor by decreasing EGFR signaling in various cancers, including head and neck cancer and non-small cell lung cancer (NSCLC)." (PMID 26919236, 2016). "AKT is an EGFR downstream signal and is involved in cell proliferation, angiogenesis, and metastasis in head and neck cancer." (PMID 26646323, 2016). "In colorectal, and head and neck cancers, KRAS mutation, EGFR-S492R mutation, and increased ErBb signaling are responsible for resistance against Cetuximab." (PMID 26904540, 2016). "EGFR expressing CAL-27 head and neck cancer (HNC) cells were treated with C-MMAE and imaged by direct fluorescence." (PMID 27698471, 2016). "Cetuximab (Erbitux/C225), an anti-epidermal growth factor receptor (EGFR) human-mouse chimeric immunoglobulinG1 (IgG1) antibody has already been approved for the treatment of head and neck cancers and colon cancer." (PMID 26883295, 2016). "The epidermal growth factor receptor (EGFR) is overexpressed in approximately 90% of HNSCC and has been implicated in the pathogenesis of head and neck cancers." (PMID 25823819, 2015). "Increased expression of EGFr has correlated with a poor prognosis for patients with head and neck cancer treated with conventional therapies." (PMID 26458879, 2015). "Although the epidermal growth factor receptor (EGFR) is an established target in head-and-neck cancer (HNC), resistance to EGFR-targeted therapy mediated by various mechanisms has been reported." (PMID 26655729, 2015). "It is interesting to note that EGFR which is generally overexpressed in head and neck cancer can induce expression of MMP-9 and leads to the activation of the Raf-MEK-ERK signal transduction pathways which in turn can activate the c-Jun transcription factor." (PMID 26581505, 2015). "Even though anti-EGFr treatments, such as cetuximab are effective in head and neck cancer, it is known that the EGFr pathway receives additional signaling input from other parallel growth pathways." (PMID 26458879, 2015). "Others have explored the dual inhibition of molecular targets as a method of enhancing the effects of radiation in head and neck cancer by targeting various aspects of EGFr signaling." (PMID 26458879, 2015).
head and neck cancer (continued). "Others have demonstrated the ability of anti-EGFR (cetuximab) radiolabeled tracers with PET scans to monitor receptor expression in Head and Neck cancers." (PMID 26569309, 2015). "In recent years, the successful application of molecular-targeted drugs, particularly anti-EGFR Mab (including cetuximab and nimotuzumab), has allowed a new choice in the concurrent therapy in head and neck cancer treatment." (PMID 25114932, 2014). "Anti-EGFR targeted therapies are currently available for head and neck cancer but with modest results." (PMID 24967412, 2014). "Studies show that EGFR is highly expressed in a variety of tumors, especially in head and neck cancer, for which the positive rate of EGFR is 80-100%." (PMID 24602316, 2014). "Currently the only FDA approved targeted agent for treatment of patients with advanced head and neck cancer is cetuximab (an EGFR-directed monoclonal antibody)." (PMID 24891850, 2014). "It has been reported that Bcl-xL is regulated by EGFR-activated STAT3 to promote survival in head and neck cancer." (PMID 24621885, 2014). "EGFR signaling, therefore, is being actively pursued as a promising target to develop therapeutics for resistant and recurrent head and neck cancer and other cancer type using small molecule inhibitors and antibodies." (PMID 24586249, 2014). "An inverse relationship between HPV status and EGFR expression has been demonstrated in several recent head and neck cancer studies." (PMID 23331666, 2013). "The epidermal growth factor receptor (EGFR) plays a vital role in head and neck cancer development, growth, and metastatic spread and angiogenesis, owing to promotion of epidermal cell growth and regulation of cell proliferation." (PMID 24455727, 2013). "The addition of a targeted agent, such as a monoclonal antibody EGFR inhibitor, has been reported to improve outcome over primary radiotherapy alone in head and neck cancers of the oropharynx, hypopharynx and larynx." (PMID 23385513, 2013). "Another anti-EGFR monoclonal antibody investigated as an agent for targeted therapies in head and neck cancer is panitumumab." (PMID 24455727, 2013). "Immunohistochemical expression of p16 and PCR of HPV16 DNA were retrospectively analyzed in tumor blocks from 108 stage III/IV head and neck cancer patients treated with RT+CT or RT+EGFR inhibitors." (PMID 23331666, 2013). "Emerging data also indicate that the epidermal growth factor (EGFR) and its signal transduction pathway play an important role in head and neck cancer." (PMID 23385513, 2013). "Cetuximab, a monoclonal antibody targeting the epidermal growth factor receptor (EGFR), is an active agent in head and neck cancer." (PMID 23373010, 2013). "HA treatment activates and promotes EGFR-mediated pathways including Ras, RhoA, Rho kinase, and phosphatidylinositol-3 (PI-3) kinase signaling in head and neck cancer." (PMID 23855374, 2013). "EGFR inhibition has been shown its efficiency in the treatment of head and neck cancer these recent years with particularly limited toxicities compared with platinum-base chemotherapy." (PMID 23445779, 2013). "An earlier study on head and neck carcinomas suggests that apigenin targets EGFR, which is upstream of PI3K/Akt." (PMID 23724790, 2013). "Cetuximab is widely used as a standard therapy for EGFR-positive colorectal and head and neck cancer, and shows clinical efficacy both alone and in combination with chemotherapeutic agents." (PMID 22139134, 2012). "The increased expression of EGFR is mainly found in head and neck cancers, in which 70-90% of the cases show this profile." (PMID 23207070, 2012). "We recently reported that cetuximab, which inhibits the EGFR signaling pathway, can generate a DNA repair defect in head and neck cancer cells and subsequently induce a contextual synthetic lethality with the PARP inhibitor ABT-888." (PMID 23071597, 2012).
head and neck cancer (continued). "Monoclonal antibodies against EGFR are increasingly used with external beam radiotherapy in the treatment of head and neck cancer patients." (PMID 22997576, 2012). "The well-established crosstalk between ER and EGFR in head and neck cancers arbitrates this action which is further validated by the colocalised membrane ER and EGFR in the lung tumors." (PMID 22363346, 2012). "Elevated expression and activity of the epidermal growth factor receptor (EGFR)/protein kinase B (Akt) signaling pathway is associated with development, progression and treatment resistance of head and neck cancer (HNC)." (PMID 23115635, 2012). "EGFR is a transmembrane receptor found in epithelial cancers such as breast, lung, bladder, ovary, prostate, and head and neck cancers." (PMID 23231994, 2012). "Despite EGFRs critical role in the development of HNSCC, clinical data indicate modest clinical benefits for locoregional control and survival of head and neck cancer patients treated with EGFR-targeted therapies." (PMID 21776391, 2011). "For example, the demonstration of improved outcomes in patients with head and neck cancers when EGFR targeting is combined with radiation will naturally lead to new EGFR-targeted therapies being assessed with radiation in head and neck cancer cell lines." (PMID 21772330, 2011). "The class of molecularly targeted therapies against the epidermal growth factor receptor (EGFR) is one such example, as EGFR is overexpressed in a number of head and neck cancers." (PMID 21299897, 2011). "The apparent cooperation between IGF-1R and EGFR in promoting HNSCC pathogenesis as well as resistance to EGFR-targeted therapy, suggests an advantage to cotargeting these signaling axes for the treatment of head and neck cancers." (PMID 21776391, 2011). "In this study, we demonstrate that C225, an inhibitor of EGFR, augments cellular susceptibility to the PARPi ABT-888 in head and neck cancer cells." (PMID 21912620, 2011). "EGFR is overexpressed in many head and neck cancers and molecular therapies targeting the EGFR/AKT signaling cascade (such as cetuximab) have been shown to increase the therapeutic efficacy of standard platinum-based chemotherapy." (PMID 21299897, 2011). "One of the future trends is development of drugs such as EGFR inhibitors that have improved outcomes in head and neck cancer treatment." (PMID 21854640, 2011). "The relevance of Met as a mechanism for escape from EGFR-targeted therapy in head and neck cancers remains to be determined." (PMID 21776391, 2011). "This patient experienced a significant reduction in joint pain during treatment with anti-EGFR/HER1 antibody cetuximab for head and neck cancer." (PMID 21982514, 2011). "Our study demonstrates that inhibition of EGFR with C225 enhances cytotoxicity with the PARPi ABT-888 in head and neck cancer cells via C225-mediated disruption of the HR- and NHEJ-mediated DSB repair pathways." (PMID 21912620, 2011). "Correlation between EGFR overexpression and response to radiotherapy has been well described in human head and neck cancers." (PMID 20509969, 2010). "EGFR is commonly expressed in cancers of the head and neck (H and N), and anti-EGFR agents have demonstrated improvements in outcomes (TTP and OS)." (PMID 21274259, 2010). "In accordance, a recent study of head and neck cancer demonstrated that activation of EGFR and HER2 was correlated with MAPK activation and that ERK1/2 inhibition by cetuximab points to these molecules as potential surrogate markers in the clinical setting." (PMID 19654571, 2009). "A number of recent studies in head and neck cancer demonstrate a low, but significant, level of clinical response (up to 12%) of single agent EGFR TKI, in a setting of recurrent or metastatic disease." (PMID 20130810, 2009). "Cetuximab, a monoclonal chimeric antibody, inhibits EGFR, which is over-expressed in the vast majority of head and neck cancers." (PMID 19527509, 2009).